LGR5 (leucine rich repeat containing G protein-coupled receptor 5)
Diseases named in the same sentence as LGR5 in open-access papers (continued):
Sharing a sentence is not in itself a finding about the gene and the disease.
cancer (continued). "EL001672 and 1′-O-methyl-averantin suppresses the cancer stemness markers such as ALDH1, CD44, CD133, Lgr-5, Msi-1 and EphB1." (PMID 36797277, 2023). "Many studies have reported that CRC cancer cells in spheroids express markers associated with stemness phenotypes such as CD133, CD44, CD44v6, CD166, and Lgr5, the latter widely used to study CRC cancer stem-like cells both in in vitro and in vivo models." (PMID 36982333, 2023). "Levels of PGE2 were found to be correlated with cancer stem cell markers including CD133, CD44, LGR5 and SOX258." (PMID 37875589, 2023). "We found that treatments enriched the expression of CSC markers CD166, ALDH1A3, CD133, and LGR5 and activated PI3K/Akt pathway in cancer cells." (PMID 37791907, 2023). "The combinational therapy was found to target cancer stem cells, as suggested by the reduction of cancer stemness factors, such as DCLK-1, CD24, Lgr5, CD29, and CD44, and the colonosphere formation." (PMID 36765950, 2023). "Leucine-rich repeat-containing G-protein-coupled receptor 5 (LGR5, GPR49, HG38, or FEX) is a glycoprotein hormone receptor involved in the development of malignant tumours." (PMID 38201468, 2023). "Up to now, Wnt/β-catenin signaling has been considered as the key factor in regulating cancer stem cells, and masses of cancer stemness-related genes (OCT4, ALDH1A1, LGR5, CD44, c-Myc, SOX2, and so on) are regulated by Wnt/β-catenin signaling." (PMID 36319622, 2022). "After it was demonstrated that LGR5+ cells have the capacity to promote gastric carcinogenesis upon mutation of Kras, other studies, including a recent one using Gpr30 as a chief cell marker, concluded that chief cells are unlikely to give rise to metaplasia and cancer lesions." (PMID 36099044, 2022). "TGFβ2 was significantly negatively correlated with mRNAsi and significantly positively correlated with cancer stem cell markers DCLK1, Lgr5, CD133 and CD44." (PMID 35620459, 2022). "While the existence of LGR5 stem cell-like cells in BE and EAC is mostly confirmed, its significance on cancer progression and metastasis remains to be determined with future studies." (PMID 35154991, 2022). "LGR5 and CD133, both markers of (different) cancer-stem cell subpopulations, were significantly affected by the ECM." (PMID 36741736, 2022). "Cancer stem cells from either human GC cell lines or tumor tissues were isolated using cell surface markers such as CD24, CD44, CD54, CD71, CD90, CD133, Lgr5, ALDH1, EpCAM, and CXCR4." (PMID 36176765, 2022). "Further PCR analysis also indicated decreased mRNA levels of cancer stem cell biomarkers in 25 μM AB4 treated HCT116/FU sphere cells, including LGR5, CD133, CD24 and POU5F1." (PMID 34890366, 2021). "Expression of LGR5 and BMI1 cancer stemness markers was significantly enhanced when cells were cultured under hypoxic conditions p<0.05." (PMID 34314381, 2021). "Accordingly, depletion of Sec62 decreased the expression of Wnt target genes including AXIN2, LGR5 and MYC, all of which play critical roles in maintaining cancer cell stemness and CRC progression." (PMID 33858476, 2021). "Previous studies have shown that the miR-340, LGR5, and FOXO1 genes have an effective role in the suppression or progression of various types of cancer as well as in the decrease or increase of drug sensitivity against chemotherapy." (PMID 33718760, 2021). "Flow cytometry analysis also showed lower percentage of LGR5+ cells in HCT116/FU-Src cells than control cells after AB4 treatment, whereas Bosutinib attenuated the cancer stem cell elimination effects of AB4/5-FU co-treatment." (PMID 34890366, 2021). "We found that high CCNP expression correlated with a high expression of Axin2 (p < 0.0001), cyclin D1 (CCND1) (p = 0.0026), Lgr5 (p < 0.0001) and Ascl2 (p < 0.0001), suggesting that CCNP and stemness are broadly intertwined in human cancer." (PMID 34604945, 2021).
cancer (continued). "Increased expression levels of LGR5, PROM1, KLF4, SOX2, and MYC in HGD and cancerous tissues support the malignant phenotype and the existence of cancer stem cells and demonstrate that they can be used to assess diagnosis and prognosis." (PMID 34452555, 2021). "Multiple markers have been identified that are present in normal intestinal and cancer stem cells, including, but not limited to CD44, CD24, CD166, CD133, telomerase (TERT), doublecortin calmodulin-like kinase 1 (DCLK1), and LGR5." (PMID 34206989, 2021). "It has come to light less lately that LGR5 triggers the activation of both Wnt and TGF-β signaling in cancer stem cells." (PMID 33489917, 2020). "Many surface markers of cancer stem cells (CSCs) (CD44, CD24, CD133, LGR5/GPR49, ABC cassette genes, EpCAM) are direct targets of the WNT pathway." (PMID 32659938, 2020). "Expression of cancer stemness markers (PROM1 and LGR5), EMT genes (SNAI1, ZEB1 gene and CDH1) and percentage of ALDH + cells were evaluated to assess the effect of sinensetin in modulating cancer stemness and self-renewal." (PMID 33628166, 2020). "This surprising outcome is associated with a moderate but detectable (15%) increase in the number of Lgr5+ CBC cells, which, in addition, display a higher degree of stemness and cancer-, inflammation- and innate immunity-related gene expression signatures." (PMID 32948837, 2020). "Three stem cell markers, LGR5 (intestinal and fallopian tube stem cell marker), SSEA3 and 4 (embryonic and cancer stem cell marker), and ALDH were chosen for further evaluation." (PMID 32035490, 2020). "In the present study, we used common stem cell markers including LGR5 (FTESC maker), SSEA3, SSEA4 (embryonic and cancer stem cell markers) and ALDH (cancer stem cell marker) to characterize the FTESC population in FTEC." (PMID 32035490, 2020). "We successfully derived FTEC with the expression of the normal stem cell markers (LGR5, SSEA3, and SSEA4), cancer stem cell markers (CD24, CD44, CD117, ROR1, CD133, and ALDH), and characteristics of stem cell." (PMID 32035490, 2020). "Many cell surface markers in stem cell and cancer stem cells are direct Wnt targets, including LGR5/GPR49, CD44, CD24, CD133, ABC cassette genes and EpCAM." (PMID 32426696, 2019). "The (cancer) stem cell markers ALDH1A1 and LGR5 were expressed at significantly higher in the rounded Wnt active cells." (PMID 31105876, 2019). "ASF1a interacts with the transcription factor β-catenin and activates the downstream genes cyclin D1, myc, Lgr5, and ZEB1, promoting cancer development and progression." (PMID 30692519, 2019). "CSCs, depended on cancer types, occupied different markers, such as, SOX2, CD133, epithelial cell adhesion molecule (EpCAM), CD166, CD24, CD29, Lgr5, Kruppel-like factor 4 (Klf4) and ALDH." (PMID 30962766, 2019). "By determining the optimal cut-off using ROC curves for each molecule, the individual sensitivity and specificity of these six molecules (NANOG, CD49f, LGR5, ΔNp63, SOX2, and CD24) for cancer detection ranged from 29.2% to 62.5% and 83.3 to 100%, respectively." (PMID 30327565, 2018). "In the present study, we first examined cellular LGR5 expression levels using datasets available through ONCOMINE, a web-based cancer microarray database." (PMID 29471794, 2018). "We also analyzed LGR5 expression in cellular datasets available through ONCOMINE, a web-based cancer microarray database." (PMID 29471794, 2018). "Lgr5 is one of target genes of theβ-catenin/WNT pathway and the marker of stem cells in small intestine and colon and potential cancer stem-like cells of CRC." (PMID 30046385, 2018). "Although the research group using Lgr5-2A-CreERT mice claimed that Lgr5+ chief cells gave rise to cancer following high-dose-tamoxifen-induced injury and mutant Kras expression, Kras activation alone does not cause histological cancer, but instead metaplasia, as in other Kras models." (PMID 30384487, 2018).
cancer (continued). "Although the anti-cancer effect of dFz7-21 has not been demonstrated in this paper, dFz7-21 was able to block Lgr5+ stem cell function, which indicated its potential ability to block FZD7 subclass in cancers." (PMID 29789460, 2018). "After transfection, we found that the three cancer cells transfected with miR-142-3p had a greater proportion of CD133- and Lgr5-positive cells than those transfected with the control." (PMID 30220706, 2018). "This phenomenon surely suggests that NANOGP8, Lgr5 and β-catenin comprise a signal transduction axis, which is responsible for all the phenotype changes observed in the NANOGP8 over-expressed cancer cells." (PMID 29689047, 2018). "Stem cell markers CD133, CD44, ABCG2, Oct4, Lgr5, and CD24 are also highly expressed in cancer stem cells." (PMID 29422082, 2018). "For all other hallmarks of cancer features promising prognostic biomarkers were identified as well, including COX-2, PAK-1, p14ARF, MET, LC3B, IGFBP7 and LGR5." (PMID 30185893, 2018). "We found that STAT3 activation (phosphorylation) and LGR5 mRNA levels were individually induced by EGF, revealing that EGFR is capable of exacerbating cancer stemness properties; this finding is consistent with that of a previous study." (PMID 30068339, 2018). "Each BP compound induced the expression of certain cancer stemness markers.1-BP strongly induced the expression of ALDH-1, CD133, Lgr-5, and Msi-1, but had little effect on CD44." (PMID 28862656, 2017). "Protein levels of cancer stem-like biomarkers (CD133, ALDH1, Lgr5, Vimentin, Snail1), and the proliferative rate of 131I-AC133.1 mAb group were lower than other groups (P<0.001); while its protein level of E-cadherin was higher than other groups." (PMID 28430648, 2017). "Quantitative PCR analyses were performed to measure the transcriptional regulation of cancer stemness markers, such as ALDH-1, CD133, CD44, Lgr-5, Msi-1, EphR1, and Bmi-1, by BP compounds." (PMID 28862656, 2017). "Colony formation and expression of LGR5 and CD133 cancer stemness markers were significantly reduced." (PMID 28394276, 2017). "In this present study, we investigated the role of Lgr5 in ESCC and ESCC spheroid body cells, which were identified as a small subset of stem-like cancer cells." (PMID 28404917, 2017). "When cancer cells were transferred back to normoxia, higher expression of SCEL and E-cadherin and lower expression of vimentin and Lgr5 were restored." (PMID 27013588, 2016). "LGR5, EPHB2, CD44s and CD44v6 were all significantly up-regulated in cancer tissues compared to normal tissues (median increase 9.4-fold, 3.5-fold, 3.0-fold and 6.4-fold respectively, all p-values <0.0005; one-sample t-tests of logged values = 1)." (PMID 26367378, 2015). "In summary, we have shown that LGR5 is expressed by ES, in particular by putative cancer stem cells and, in the context of a Wnt and RSPO-rich microenvironment, LGR5 functions to potentiate canonical Wnt/β-catenin signaling." (PMID 23596566, 2013). "Elevated expression of stem cell marker genes represents cancer stemness in Lgr5 positive cells compared to Lgr5 negative cells." (PMID 38659853, 2024). "As LGR5 is an important intestinal and cancer stem cell marker, this suggests EREG may be involved in cancer stemness." (PMID 40727266, 2024). "Genes of WNT/β-catenin signaling and several stem cell signatures were predominantly ITH-low, but a small subset of genes in the LGR5 and EPHB2 cancer stem cell signatures had high scores, which contributed to the correlation of these signatures with PC1 of ITH-high genes." (PMID 38773143, 2024). "In addition, a higher expression of Hakai and Lgr5 proteins was detected in cancer stem cell tumourspheres, while CBLL1 silencing reduces the tumoursphere size and downregulates the Lgr5 biomarker." (PMID 38339195, 2024).
cancer (continued). "Cancer stem cells are identified and can be isolated based on the expression of specific cell-surface proteins that act as molecular biomarkers, among which the most frequent markers are CD44, CD133, CD24, EpCAM, and LGR5." (PMID 37367867, 2023). "To evaluate whether canonical Wnt pathway inhibition affects the proportion of the CSC subpopulation, we determined the expression of cancer stem cell markers such as CD133 and Lgr5 that increased in spheroid cultures." (PMID 36982333, 2023). "The markers most frequently used to identify cancer stem cells in solid tumors are CD44, CD133, CD24, epithelial cell adhesion molecule (EpCAM), interleukin 6 (IL-6) receptor, and leucine-rich repeat-containing G-protein coupled receptor 5 (LGR5)." (PMID 37237922, 2023). "In addition to and most likely due to the abilities of LGR5 and RSPO3 to regulate β-catenin signaling, they are also employed as cancer stem cell markers." (PMID 37998393, 2023). "Cancer stem cells are supposed to be resistant to the various anti-cancer therapies and an obstacle against treatments, and stem cell biomarkers have been identified such as CD44, CD133, Ascl2, and Lgr5 in CRC." (PMID 37098074, 2023). "It has been indicated that LGR5 could induce cell mobility, invasion, tumorigenesis, and EMT in cancer cells through activation of the Wnt/β-catenin pathway." (PMID 36740668, 2023). "Previous research showed that overexpression or knockout of LGR5 resulted in pronounced changes of the cytoskeleton and cell adhesion complexes in some cancer cell lines lacking endogenous or exogenous RSPO stimulation." (PMID 37770230, 2023). "In our study, we found that RAI2 suppressed the expression of ASCL2 and LGR5 by Western blot in CRC cells, and we also found a negative correlation between RAI2 and ASCL2/LGR5 in 298 cases of cancer tissues from CRC patients by IHC detection." (PMID 35299743, 2022). "Calcitriol increases the expression of stemness-related genes, such as the leucine-rich repeat-containing G protein-coupled receptor 5 (LGR5), SMOC2, LRIG1, MEX3A, MSI1, and PTK7, attenuating the transformation into cancer stem cells, and, therefore, impacts tumorigenesis at a very early stage." (PMID 36364774, 2022). "As AKT or MAPK signaling pathways are often involved in cancer cell survival, we examined the activation of AKT and ERK proteins and found that LGR5 overexpression resulted in the downregulation of AKT and ERK phosphorylation as well as AKT and ERK protein levels." (PMID 35778589, 2022). "Cancer stem cell markers, such as LGR5 and CD133, are not able to distinguish CSCs from normal tissue stem cells." (PMID 36372898, 2022). "The results demonstrated that the inhibitor could effectively suppress all stem gene expressions including CD133, Lgr5, and TGF-β1 in HCT-116 cancer cells and in dose-dependent manners." (PMID 36386200, 2022). "SATB2 may be a driving force for developing cancer stem‐like phenotypes in damaged hepatocytes where induction of stem cell markers (CD44, CD90, EpCAM, AFP and LGR5) and pluripotency maintaining factors (POU5F1/Oct4, Sox‐2, Nanog and KLF4) was prominent." (PMID 35152538, 2022). "Finally, combined treatment was able to significantly downregulate LGR5 and Notch1 in SW620 cancer stem cell (CSC) colonospheres." (PMID 34959725, 2021). "LGR5 stimulation of Wnt and TGF-b signaling in cancer stem cells has just recently been discovered." (PMID 34452555, 2021). "Cancer stem cell markers also include NANOG, ALDH1, SOX2, OCT4, LGR5, CD44, and CD133; therefore, stemness may be judged by the expression of these markers." (PMID 34725550, 2021). "Our results suggest that Lgr5 signaling is not an essential driver of some cancers arising after introduction of cancer-initiating genetic alterations into Lgr5+ stem cells." (PMID 31901081, 2020). "BMP7 expression was limited to the apical part and absent in the LGR5+ stem cells located at the very base of the cancer gland." (PMID 31591478, 2020).
cancer (continued). "Using this model, it was found that in the absence of cancer stem cells, liver metastases did not occur, whereas primary tumors did not regress, indicating that Lgr5-positive cancer stem cells are required for metastasis." (PMID 33135109, 2020). "However, we did not observe down-regulation of other stem cell markers (CD133 and Lgr5), suggesting that both MUC5AC and CD44 have a positive role in maintaining a specific subset of the cancer stem cell population." (PMID 32098629, 2020). "Moreover, it was able to target cancer stemness and self-renewal ability by reducing (i) ALDH1 activity, (ii) the expression of stemness-related genes (PROM1, LGR5), and (iii) the colony formation ability." (PMID 30717428, 2019). "Cytotoxicity was induced in LGR5-overexpressing cancer cells, but not in LGR5-negative cells or cell lines where LGR5 had been knocked down." (PMID 30984612, 2019). "Moreover, cancer stemness related genes such as CD44, CD133, LGR5, LSD1, OCT4, Sox2 and Sox9 were co-upregulated with LETM1 in A549 cells." (PMID 31500591, 2019). "Collectively, these studies suggest that Lgr5 may play an important role in the Treg- and TGF-β1-mediated cancer immunosuppressive microenvironment, although the exact immunological mechanism is still unknown." (PMID 31417548, 2019). "PKM2-intact Lgr5-GFP− or Lgr5-GFP+ ISC-derived cancer cells in colon polyps did not express PKM1 in PKM2ΔLgr5-Tx or PKM2ΔLgr5-Veh mice." (PMID 30996297, 2019). "The results showed that YTHDF1 silencing formed smaller tumors.Then we validated the expression of CD133, CD44, ALDH1, OCT4, and Lgr5 in xenograft tumors by RT-qPCR, the results showed that YTHDF1 silencing downregulated the expression of CRC cancer stem cell markers in xenograft tumors." (PMID 31131257, 2019). "We showed NANOGP8 activates β-catenin but not reversal because forced expression Lgr5 in cancer cells had no impact on NANOG1/NANOGP8 expression." (PMID 29689047, 2018). "For example, although MCC shows expression values contrary to the rest of skin states in the identified DEGs, there are genes like LGR5, POU4F1, SOSTDC1, KRT20 and MYO15A which are clearly postulated as differentiating genes in MCC diagnosing in comparison to other cancer-related skin states." (PMID 29750795, 2018). "EGF significantly induced STAT3 phosphorylation and elevated the mRNA levels of LGR5 in the HT29 cells, implying that addition of EGF activated STAT3 in the cancer stem-like tumorspheres, thus contributing to the formation and survival of EGFR-positive CRC stem-like tumorspheres." (PMID 30068339, 2018). "In addition, mRNA expressions and protein levels of cancer stem markers aldehyde dehydrogenase-1 (ALDH1), cluster of differentiation 133 (CD133), CD44, Lgr5, and Musashi-1 were reduced after tumidulin treatment." (PMID 30441806, 2018). "In regard to cancer, stem cells are relatively resistant to chemotherapeutic agents, and increased levels of LGR5 correlate with chemoresistance, suggesting that LGR signaling may promote the recovery of a cancer stem cell population following chemotherapy." (PMID 29416699, 2018). "LGR5 expression is evaluated during cancer cell metastases that can be attributed to both LGR5-positive and -negative carcinomas." (PMID 30089773, 2018). "For example, several genes from the final part of the ranking, present specific clear information on MCC against the rest skin states as LGR5, POU4F1, SOSTDC1, KRT20, TGM3 and MYO15A genes, as their gene expression levels are opposite against to the other cancer-related skin states." (PMID 29750795, 2018). "In contrast, the analysis of LGR5+ cell populations in human cancers has been hampered by the lack of good commercial antibodies that recognize this protein at the cell surface." (PMID 28468934, 2017).